SNORD116-15 (small nucleolar RNA, C/D box 116-15)
Synonyms: HBII-85-15
Gene: Small nucleolar RNA gene on chromosome 15 (25,081,287 to 25,081,378, forward strand). Ensembl gene ENSG00000207174.
Gene Ontology:
Biological process: RNA processing
Cellular component: nucleolus
Homologues: Orthologues: chimpanzee SNORD116 (100% identical), macaque SNORD116 (98% identical), guinea pig SNORD116 (89% identical), guinea pig SNORD116 (85% identical). Paralogues in human: SNORD116-17 (99% identical), SNORD116-19 (99% identical), SNORD116-14 (98% identical), SNORD116-18 (98% identical), SNORD116-20 (98% identical), SNORD116-21 (98% identical), SNORD116-22 (98% identical), SNORD116-16 (96% identical), SNORD116-23 (95% identical), SNORD116-12 (92% identical), SNORD116-24 (92% identical), SNORD116-11 (89% identical), and 19 more.